SNHG1 (small nucleolar RNA host gene 1)
Diseases named in the same sentence as SNHG1 in open-access papers (continued):
Sharing a sentence is not in itself a finding about the gene and the disease.
hepatocellular carcinoma (36 papers, 2017 to 2025). A malignant tumor that arises from hepatocytes. "Poor prognosis associated with SNHG1 lncRNA expression leads to colon cancer tumorigenesis, hepatocellular carcinoma, and the proliferation of non-small cell lung cancers." (PMID 39257589, 2024). "In hepatocellular carcinoma, sorafenib resistance is caused by miR-21 enhancement of SNHG1 which leads to SNHG1 retention in the nucleus and enhances transcription of SLC3A2 and activation of the AKT pathway." (PMID 35582574, 2019). "Previous research has indicated that SNHG1 is highly expressed in hepatocellular carcinoma, where it mediates sorafenib resistance through activating the AKT pathway and is linked to poor prognosis." (PMID 38331968, 2024). "For example, in the turquoise module, the SNHG1 gene has been shown to be involved in cancer regulation, including hepatocellular carcinoma, through multiple ceRNA pathways." (PMID 36479313, 2022). "Small nucleolar RNA host gene 1 (SNHG1) is identified as one kind of lncRNA and involved in several cancers’ regulation, such as colon cancer, hepatocellular carcinoma, and NB." (PMID 36130928, 2022). "The novel TCPOBOP-inducible lncRNAs include lnc4278/Dancr, lnc14777/Snhg1, and lnc10895/Snhg10, which promote hepatocellular carcinoma through their actions as miRNA sponges, and lnc733/Gas5, which is also a miRNA sponge and acts to inhibit liver fibrosis." (PMID 33761883, 2021). "The purpose of the study is to explore the potential competing endogenous RNA (ceRNA) network and investigate the molecular mechanism of long noncoding RNA (lncRNA) small nucleolar RNA host gene 1 (SNHG1) in hepatocellular carcinoma (HCC) development." (PMID 34917510, 2021). "Expression and survival analyses demonstrated that, among these predicted lncRNAs, SNHG1, HCG18, NUTM2A-AS1 and ASB16-AS1, and SNHG6 were markedly upregulated in hepatocellular carcinoma and linked to poor prognosis." (PMID 32257949, 2020). "Through a similar mechanism, lncRNA SNHG1 binds to miR-195-5p to enhance the proliferative and migratory capabilities of hepatocellular carcinoma cells." (PMID 32199129, 2020). "LncRNA-small nucleolar RNA host gene 1 (SNHG1) is upregulated in sorafenib-resistant hepatocellular carcinoma cells compared to parental lines." (PMID 35582574, 2019). "SNHG1 is upregulated in hepatocellular carcinoma, and the upregulated expression of SNHG1 predicts a poor prognosis." (PMID 29416759, 2018). "Long noncoding RNA SNHG1 predicts a poor prognosis and promotes hepatocellular carcinoma tumorigenesis and SNHG1 exacerbates hepatocellular carcinoma through suppressing miR-195." (PMID 29340086, 2017). "The lncRNA SNHG1, which is involved in several cancers, such as hepatocellular carcinoma and non-small cell lung cancer, was functionally associated with PAICS and IMPDH2 in this subpathway." (PMID 28152521, 2017). "SNHG1 expression was significantly upregulated in both hepatocellular carcinoma and non-small cell lung cancer when compared with corresponding normal tissues and cells, and in vitro assays showed that knockdown of SNHG1 inhibited tumor cell proliferation." (PMID 28212545, 2017). "For example, SNHG1 soaks up miR-195-5p to regulate PDCD4 expression in hepatocellular carcinoma." (PMID 32497022, 2020). "Of note, lncRNA Snhg1 is reported to be increased in hepatocellular carcinoma." (PMID 31269941, 2019). "LncRNA small nucleolar RNA host gene 1 (SNHG1) was significantly overexpressed in several tumor tissues compared with adjacent normal tissues, and it promoted the proliferation of a variety of tumors, such as lung cancer, colorectal cancer and hepatocellular carcinoma." (PMID 37127605, 2023). "In addition, STEAP3-AS1 also displayed an oncogenic role in human hepatocellular carcinoma (HCC) by acting as a competing endogenous RNA (ceRNA) and served as a risk scoring system together with three other lncRNAs (SNHG1, RUSC1-AS1, and SNHG3) to predict the outcomes of HCC patients." (PMID 35986274, 2022).
hepatocellular carcinoma (continued). "We used sequencing data downloaded from Genomic Data Commons to analyse the expression and interaction networks of SNHG1 in hepatocellular carcinoma (HCC)." (PMID 33499863, 2021). "Moreover, it's reported that SNHG1 may contribute to the aggravation of hepatocellular carcinoma through the inhibition of miR-195." (PMID 29416759, 2018). "Enhanced SNHG1 (small nucleolar RNA host gene 1) expression has been found to play a critical role in the initiation and progression of hepatocellular carcinoma (HCC) with its detailed mechanism largely unknown." (PMID 33009370, 2020). "In the present study, we explored the roles and interactions of oncogenic lncRNA small nucleolar RNA host gene 1 (SNHG1), miR-376, forkhead box protein K1 (FOXK1), and Snail in hepatocellular carcinoma (HCC)." (PMID 34095464, 2021).
colorectal cancer (32 papers, 2017 to 2026). A primary or metastatic malignant neoplasm that affects the colon or rectum. "In colorectal cancer cells and tissues, SNHG1 is increased in expression and is associated with decreased patient survival." (PMID 35236381, 2022). "SNHG1 has been reported to be up-regulated in non-small cell lung cancer; in colorectal carcinoma and laryngeal carcinoma, it has been associated with cancer stage, the presence of metastasis, and a worse prognosis." (PMID 33643897, 2020). "The expression of SNHG1 was associated with advanced stage and tumor recurrence of colorectal cancers." (PMID 29416759, 2018). "Our analysis revealed that SNHG1 was upregulated in human colorectal cancer tissues, and high SNHG1 expression was associated with reduced patient survival." (PMID 30266084, 2018). "To further explore the underlying molecular mechanisms by which SNHG1 regulated downstream effectors in colorectal cancer, we firstly identified its localization in cancer cells given that lncRNA functions are dependent on its subcellular localization." (PMID 30266084, 2018). "Finally, correlation analysis revealed that SNHG1 expression is negatively associated with miR-154-5p in 30 colorectal cancer tissues (P = 0.008)." (PMID 30266084, 2018). "Moreover, correlation analysis revealed that SNHG1 expression was positively associated with CCND2 expression in 30 colorectal cancer tissues (P = 0.036)." (PMID 30266084, 2018). "After knockdown of SNHG1, cell growth were inhibited; however, this cell growth suppression effect conferred by loss of SNHG1 could be rescued by inhibition of endogenous miR-145 in colorectal cancer cells (*, p<0.05)." (PMID 29416759, 2018). "SNHG1 is upregulated and is mainly localized in the nucleus of gastric cancer, colorectal cancer, liver cancer, and lung cancers." (PMID 40510136, 2025). "For example, SNHG1 contributes to the progression of colorectal cancer by interacting with EZH2 and miR-154-5p15, whereas inhibition of SNHG1 reduces prostate cancer cell growth and metastasis." (PMID 38331968, 2024). "SNHG1 has also been reported to be involved in tumor development including colorectal cancer and osteosarcoma." (PMID 34917510, 2021). "MiR-137 has been found to interact with long non-coding RNA (lncRNA) small nucleolar RNA host gene 1 (SNHG1) in the tumorigenesis of colorectal cancer (CRC)." (PMID 33685449, 2021). "SNHG1 is also a crucial regulator of colorectal cancer cell proliferation by interacting with miR-145 and SNHG1 promotes pancreatic cancer cell growth via regulation of the PI3K/AKT pathway." (PMID 32497022, 2020). "Lastly, we determined the relationship between SNHG1 expression and prognosis in patients with colorectal cancer." (PMID 29416759, 2018). "Reciprocally, upregulation of SNHG1 repressed the expression of miR-145 in colorectal cancer cells (*, p<0.05)." (PMID 29416759, 2018). "In this study, we report that the small nucleolar RNA host gene 1 (SNHG1) is involved in colorectal cancer progression." (PMID 30266084, 2018). "By analyzing datasets downloaded from The Cancer Genome Atlas (TCGA) and Gene Expression Omnibus (GEO), we found lncRNA SNHG1 was significantly overexpressed in colorectal cancer." (PMID 30266084, 2018). "In this study, SNHG1 was upregulated in colorectal cancers, and SNHG1 expression was correlated with advanced colorectal cancer stage and tumor recurrence." (PMID 29416759, 2018). "The results showed that SNHG1 was positively correlated with target genes of miR-145 in colorectal cancers (SNHG1 and p70S6k: r: 0.353, p= 3.57E -11; E2F3: r: 0.582, p= 1.86E -31)." (PMID 29416759, 2018).
colorectal cancer (continued). "In consistent with previous studies, our data revealed that SNHG1 promotes cell proliferation by acting as a sponge of miR-145, and as a result, target genes of miR-145 were modulated by SNHG1 in colorectal cancer." (PMID 29416759, 2018). "SNHG1 expression was upregulated in all six colorectal cancer cell lines (HCT-29, DLD-1, SW-620, HCT-8, HCT-116 and SW-480) compared with the human colorectal epithelial cell FHC." (PMID 30266084, 2018). "In conclusion, our study found that SNHG1 was overexpressed in colorectal cancer and promotes cell proliferation by acting as a sponge of miR-145 in colorectal cancer cells." (PMID 29416759, 2018). "The results indicated that endogenous expression levels of SNHG1 and miR-145 were negatively correlated with each other in colorectal cancer cells." (PMID 29416759, 2018). "Our results suggest a strategy for targeting SNHG1 as a potential biomarker and a therapeutic target in colorectal cancer patients." (PMID 30266084, 2018). "(e) The relation between KLF2 and SNHG1 expression analyzed in colorectal cancer samples from TCGA cohort (n = 478, r = − 0.24, P < 0.001)." (PMID 30266084, 2018). "SNHG1 promotes colorectal cancer cell growth through epigenetic silencing of KLF2 and CDKN2B in the nucleus." (PMID 30266084, 2018). "Overall, above results indicate that SNHG1 overexpression in colorectal cancer is at least partly due to SP1 activation." (PMID 30266084, 2018). "To investigate the potential mechanisms by which SNHG1 contributed to the malignant phenotypes of colorectal cancer cells, we first examined its subcellular localization given that the function of one lncRNA depended on its subcellular distribution." (PMID 30266084, 2018). "Collectively, these results suggest that SNHG1 released CCND2 by sequestering endogenous miR-154-5p in colorectal cancers cells." (PMID 30266084, 2018). "(c) The relation between SP1 and SNHG1 expression analyzed in colorectal cancer samples from TCGA cohort (n = 478, r = 0.202, P < 0.001)." (PMID 30266084, 2018). "Taken together, these results indicate that SNHG1 promotes colorectal cancer cell growth by affecting cell cycle progression and apoptosis." (PMID 30266084, 2018). "We found that SNHG1 promoted cell proliferation by acting as a sponge of miR-145, a well known tumor suppressor of colorectal cancer." (PMID 29416759, 2018). "CCK-8 results revealed that silencing of KLF2 or CDKN2B (P15) partially abolished SNHG1 knockdown induced growth arrest of colorectal cancer cells." (PMID 30266084, 2018). "To identify the reason for high SNHG1 expression in colorectal cancer, we analyzed potential transcription factors binding sites in the SNHG1 promoter region." (PMID 30266084, 2018). "(j) The relation between CCND2 and SNHG1 expression analyzed in colorectal cancer samples from TCGA cohort (n = 478, r = 0.21, P = 0.003)." (PMID 30266084, 2018). "Next, we analyzed the correlation between the expression of SNHG1 and their clinical characteristics in colorectal cancer." (PMID 29416759, 2018). "Our study reveals that SNHG1 can display diverse regulatory mechanisms in different subcellular locations, and downstream factors of SNHG1 can form a network to regulate colorectal cancer cell growth." (PMID 30266084, 2018). "Across a large collection of different cancer types, the expression of SNHG1 was abundant in colorectal cancer cell lines." (PMID 29416759, 2018). "Collectively, these results suggested that SNHG1 promotes cell proliferation by suppression of miR-145 in colorectal cancer cells." (PMID 29416759, 2018). "Collectively, these results suggested that higher expression of SNHG1 predicts poor prognosis in colorectal cancer." (PMID 29416759, 2018). "In consistent with these findings, our data showed that SNHG1 was overexpressed in colorectal cancers." (PMID 29416759, 2018). "(f) The relation between CDKN2B and SNHG1 expression analyzed in colorectal cancer samples from TCGA cohort (n = 478, r = − 0.20, P < 0.001)." (PMID 30266084, 2018).
colorectal cancer (continued). "We then analyzed two independent microarray datasets downloaded from GEO, SNHG1 is also significantly upregulated in colorectal cancer." (PMID 30266084, 2018). "To investigate potential regulators of SNHG1 overexpression in colorectal cancer, we used the JASPAR CORE database to search transcription factor binding sites in SNHG1 promoter." (PMID 30266084, 2018). "Taken together, the results of this study indicate that SNHG1 functions as an oncogene in colorectal cancer." (PMID 30266084, 2018). "The results of our study demonstrated that SNHG1 was significantly upregulated in human colorectal cancer tissues, and its high expression was correlated with poor prognosis." (PMID 30266084, 2018). "Then, co-expression of SNHG1 and miR-145 were analyzed through querying open database ChIPBase v2.0 in TCGA colorectal cancer datasets." (PMID 29416759, 2018). "We then confirmed that the relative expression level of SNHG1 in colorectal cancer tissues (n=104) compared to corresponding normal counterparts (n=104) by qRT-PCR, and normalized to GAPDH." (PMID 29340086, 2017). "Then, we performed Histone-DNA ELISA assay to further evaluate the apoptosis in colorectal cancer cells of SNHG1 knockdown." (PMID 29340086, 2017). "Then, we explored the expression of SNHG1 in a panel of colorectal cancer cells (SW480, HCT116, HT-29, LOVO and CaCO-2) and normal intestinal mucous cell line (CCC-HIE-2) by qRT-PCR." (PMID 29340086, 2017). "In this work, we firstly found that SNHG1 expression levels were upregulated aberrantly in colorectal cancer tissues and colorectal cancer cell lines." (PMID 29340086, 2017). "The relationship of SNHG1 expression level with the clinicopathological factors in colorectal cancer was assessed." (PMID 29340086, 2017). "The SNHG1 level was potently augmented in colorectal cancer tissues compared to corresponding normal counterparts (P<0.001)." (PMID 29340086, 2017). "High expression of SNHG1 in patients with colorectal cancer can interact with EZH2 to regulate histone methylation of Krüppel-like factor 2 (KLF2) and cyclin-dependent kinase inhibitor 2B (CDKN2B) in the nucleus and affect the biological behavior of colorectal cancer cells." (PMID 40226409, 2023). "SNHG1 is aberrantly expressed in many cancers, including lung cancer, colorectal cancer, gastric cancer, and liver cancer, and maybe oncogenic leading to tumorigenesis in these cancer types." (PMID 32497022, 2020). "Notably, both of KCNQ1OT1 and SNHG1 were significantly up-regulated in tumor tissues and possessed excellent ability in distinguishing colorectal cancer patients." (PMID 33194594, 2020). "Upregulation of SNHG1 is involved in the progression of cell growth in colorectal cancer." (PMID 33224198, 2020). "Knockdown of SNHG1 significantly suppresses the growth of CRC (colorectal cancer) cells." (PMID 33224198, 2020). "For example, SNHG1 affects colorectal cancer cell growth via regulation of EZH2 and miR-154-5p." (PMID 31615767, 2019). "Besides, the SNHG1 expression in different tumor stages of colorectal cancer in TCGA cohort was shown in." (PMID 30266084, 2018). "Taken together, the results of our studies illuminate how SNHG1 formed a regulatory network to confer an oncogenic function in colorectal cancer and suggest that SNHG1 may serve as a potential target for colorectal cancer diagnosis and treatment." (PMID 30266084, 2018). "However, no significant changes in cell death were observed after knockdown of endogenous SNHG1 expression in colorectal cancer cells." (PMID 29416759, 2018). "The key finding of this study is that SNHG1 plays a vital role in colorectal cancer progression." (PMID 30266084, 2018). "Besides, through analyzing colorectal cancer RNA sequencing data in TCGA, we found SNHG1 expression was positively correlated with EZH2, SUZ12 and EED." (PMID 30266084, 2018).